AR (androgen receptor)
Diseases named in the same sentence as AR in open-access papers (continued):
Sharing a sentence is not in itself a finding about the gene and the disease.
prostate carcinoma (continued). "The findings suggest that AR-expressing myofibroblasts inhibit prostate cancer progression through paracrine signals that slow proliferation and induce apoptosis in the cancer cells." (PMID 29721186, 2018). "mTOR is the downstream gene that is positively regulated by AR in prostate cancer cells, and the repression of the mTOR signal also exhibits a compensatory increase in AR function." (PMID 29713287, 2018). "AR is an excellent target for therapy, as it has been shown historically to be an effective target for prostate cancer treatment." (PMID 29731997, 2018). "The current study adds information to this classification of prostate cancer bone metastasis by finding high bone cell activity primarily in patients with low AR activity and ongoing inflammation." (PMID 29670000, 2018). "Here, we introduce key concepts to understand how epigenetic dysregulation is a plausible driving mechanism in the reprograming of prostate cancer cells as they lose AR-imposed identity." (PMID 29888169, 2018). "Many AR co-regulatory proteins have been identified in prostate cancer and there is substantial overlap with those identified in breast cancer, however not necessarily associated with AR as of yet." (PMID 30416486, 2018). "SPDEF is also regulated by AR signalling in prostate cancer, which has both beneficial and potentially detrimental effects when AR signaling is inhibited by androgen deprivation therapy (ADT)." (PMID 30200227, 2018). "AR is a direct target for MDM2-mediated ubiquitylation in prostate cancer cells Of interest, MDM2 activation by phosphorylation is negatively regulated by the downstream target genes of AR signaling." (PMID 29713287, 2018). "More recently, effects of 27HC have been studied in both androgen-responsive LNCaP (AR+) cells and androgen-irresponsive PC3 (AR-) prostate cancer cells." (PMID 30719023, 2018). "Other studies report that the ERK cascade is phosphorylated in reaction to AR, leading to cell cycle progression in prostate cancer." (PMID 30061836, 2018). "This conclusion was well illustrated by the observation that the AR phosphorylation kinase gene CDK5 undergoes isoform switching between prostate cancer and benign tissues." (PMID 30367578, 2018). "The TMRPSS2-ERG gene fusion is found in ~50% of all primary prostate cancer samples, and provided the most-potent patient stratification based on transcriptomic, AR cistromic, and epigenetic classification." (PMID 30464211, 2018). "We propose a new V-ATPase-dependent mechanism to inhibit androgen receptor expression in prostate cancer cells involving defective endosomal trafficking of iron and the inhibition of HIF-1 α-subunit turnover." (PMID 29988966, 2018). "The mechanisms of acquiredresistance to antihormone therapies for prostate cancer can be categorized based either onthe dependence on the AR or dependence on the ligand." (PMID 29162647, 2018). "Together, these data indicate that the HDAC3 inhibitor blocks PTEN‐mutated prostate cancer cell growth by targeting both AKT and AR signaling." (PMID 29523594, 2018). "Androgen blockage with ADT was also shown to enhance the response of AR-overexpressing prostate cancer cells to T cell-mediated killing." (PMID 30121970, 2018). "The androgen receptor (AR) plays a key role in prostate cancer progression and, as a result, targeting of AR signaling is a major therapeutic strategy." (PMID 29531259, 2018). "LSD1 is an important enzyme involved in AR regulation and prostate cancer that interacts with AR and can stimulate [14••] or suppress the transcriptional expression depending on promoter/enhancer context." (PMID 29888169, 2018). "In this study, we discovered that BMI1, independently of the PRC1 complex, binds and stabilizes AR proteins to regulate the AR pathway in prostate cancer." (PMID 29402932, 2018).
prostate carcinoma (continued). "After exposure to Ang1–7 a significant up-regulation of AR expression was observed in androgen-dependent prostate cancer cells while a significant down-regulation was seen in the androgen-independent cells." (PMID 30361641, 2018). "There was a significant reduction in the cell count of each of the prostate cancer lines when co-cultured with PShTert-AR myofibroblasts." (PMID 29721186, 2018). "As expected, we confirmed that C21 treatment suppressed the proliferation activity and down-regulated the expression of AR in prostate cancer in both in vitro and in vivo experiments." (PMID 29568400, 2018). "Androgen receptor (AR) is a transcription factor that plays a key role in the initiation and progression of prostate cancer." (PMID 29464071, 2018). "The androgen receptor (AR) found in the prostate plays a role in regulating the G1/S phase transition of the cell cycle in prostate cancer." (PMID 29568320, 2018). "Androgen receptor (AR) is a ligand-activated transcription factor that plays a pivotal role in the development and progression of many severe diseases such as prostate cancer, muscle atrophy, and osteoporosis." (PMID 30639122, 2018). "The functional interactions between ELK1 and AR signaling pathways have been documented in prostate cancer cells." (PMID 29518027, 2018). "Like other prostate cancer lines, AR re-expressed in PC3 cells displays R1881- and DHT-induced release of Hsp90 and Hsp70, which reflects conformational changes induced by androgen binding to the AR ligand binding domain." (PMID 30305041, 2018). "Three genes closely related to AR functions in prostate cancer, AR, KLK3 and MAPK3, are among the detected DE genes." (PMID 30367578, 2018). "The p52 subunit can also activate AR signaling, which, in addition to induction of metabolic reprogramming of prostate cancer cells through induction of genes for glucose uptake and metabolism, contributes to androgen-independent growth." (PMID 30158439, 2018). "It is well understood that AR protein is a central driving force in prostate cancer that persist in CRPC." (PMID 29765513, 2018). "On the other hand, the prognostic significance of AR expression in the progression of prostate cancer and CRPC still remains controversial." (PMID 29555975, 2018). "Here, the authors comprehensively profile 100 primary prostate carcinomas by sequencing RNA transcripts in combination with ChIP-sequencing for AR and the active histone marks H3K27ac, H3K4me3 and repressive mark H3K27me3." (PMID 30464211, 2018). "This tumorigenic action of AR is most extensively studied in prostate cancer, where differential AR-DNA binding profiles can classify prostate cancer patients on outcome." (PMID 29396493, 2018). "As AR is the key-driving transcription factor in prostate cancer, tightly controlled by epigenetic regulation, integrating these datastreams has the potency to reveal distinct biological features for a tumor type classically-known as difficult to classify." (PMID 30464211, 2018). "Specifically, ARCC-4 is better than enzalutamide at inducing apoptosis and inhibiting proliferation of AR-amplified prostate cancer cells." (PMID 30271980, 2018). "Our data support a unique feed-forward mechanism that exploits the role of AR in prostate cancer resistance to therapy to become lethally addicted to [225Ac]hu11B6." (PMID 29691406, 2018). "The majority of these compounds are repurposed AR antagonists presently utilized in the treatment of prostate cancer." (PMID 30416486, 2018). "The cross talk between AR and ER (alpha or beta) in human breast and prostate cancer cells has been known for long time." (PMID 29651273, 2018). "As a result, AR knockdown resulted in p62 decreasing and LC3II enhancement; while the effect of DHT on prostate cancer cells was eliminated in AR knockdown cells." (PMID 30200999, 2018).
prostate carcinoma (continued). "Blocking the AR signaling is the mainstay in prostate cancer therapy, evidenced by the next-generation antiandrogens, e.g., abiraterone and enzalutamide that potently inhibit AR functions can suppress castration-resistant prostate cancer (CRPC) tumor growth." (PMID 29402932, 2018). "In prostate cancer, CpdA was shown to act as a combined AR antagonist and GR agonist, resulting in the inhibition of prostate tumor growth and the induction of apoptosis in vitro." (PMID 29738549, 2018). "We use CPRC prostate cancer model and demonstrate that endothelial cells secrete large amount of CCL5 and induces autophagy by suppressing AR expression in prostate cancer cell lines." (PMID 30200999, 2018). "Uro-A exerted cytotoxic effects against androgen receptor positive (AR+) LNCaP, C4-2B and enzalutamide-resistant C4-2B prostate cancer cells." (PMID 30441778, 2018). "The majority of prostate cancers are dependent on androgens and activation of the androgen receptor (AR) for growth and survival, and androgen deprivation therapy remains the mainstay of treatment for advanced prostate cancer." (PMID 29523594, 2018). "Similar results were seen in direct co-cultures with AR-negative DU145 and AR-positive LNCaP and C4-2B prostate cancer cell lines." (PMID 29721186, 2018). "The expression of E6-AP protein in invasive prostate cancer was lower than that of adjacent normal tissue, whereas E6-AP overexpression in stable cell lines resulted in decrease of AR protein level." (PMID 29707137, 2018). "Here, to comprehensively study the epigenetic landscape, we perform RNA-seq with ChIP-seq for AR and histone modification marks (H3K27ac, H3K4me3, H3K27me3) in 100 primary prostate carcinomas." (PMID 30464211, 2018). "In contrast, miR-652 expression in LNCaP prostate cancer cells induced NED through a pathway initiated by PPP2R3A inhibition, resulting in increased AKT, ERK-1/2 and Wnt activation, loss of AR, with gene transcription via activated β-catenin." (PMID 29721191, 2018). "ELF5 was also found to physically interact with AR in prostate cancer cells and repress its transcriptional activity." (PMID 30200227, 2018). "In AR-independent prostate cancer PC3 cells, sorafenib induces caspase-dependent cell death and this is potentiated by autophagy inhibition, whereas in AR-independent DU145 prostate cancer cells, it induces necroptosis and this is autophagy-dependent." (PMID 29371637, 2018). "We propose that targeting the androgen receptor for degradation via Proteolysis Targeting Chimeras (PROTACs) will be a better therapeutic strategy for targeting androgen receptor signaling in prostate cancer cells." (PMID 30271980, 2018). "The androgen receptor (AR) is a ligand-dependent transcription factor that promotes prostate cancer (PC) cell growth through control of target gene expression." (PMID 29707137, 2018). "AR is the driving transcription factor in prostate cancer and the primary therapeutic target for systemic treatment." (PMID 30117261, 2018). "Together, the data revealed that AR-NTD-targeting drugs are a feasible intervention for taxane-resistant prostate cancers that are driven by AR-Vs." (PMID 30453546, 2018). "One such GEF is VAV3, which is overexpressed in androgen independent prostate cancer cells and tissues, and up-regulates AR activity in prostate cancer cells." (PMID 30558664, 2018). "The studies to mimiclong-term antiandrogen therapy in prostate cancer were performed using LNCaP cells, apopular AR-positive human cell line." (PMID 29162647, 2018). "The most active macrocycle inhibits both Wnt and AR-signaling in prostate cancer cell lines, and markedly diminishes their proliferation." (PMID 30352998, 2018).
prostate carcinoma (continued). "When the androgen receptor was deleted together with a protein that normally suppresses the formation of tumors, it protected the mice from prostate cancer." (PMID 29334357, 2018). "We show that SPRY2 loss leads to an androgen self‐sufficient form of CRPC representing an ARPC (AR‐active prostate cancer) type of clinical CRPC." (PMID 29540470, 2018). "Together, these results indicate that V-ATPase function is required for AR expression and link V-ATPase function to the PSA-AR axis in prostate cancer." (PMID 29988966, 2018). "In this study, we introduce a strategy that takes advantage of the oncoaddiction of prostate cancer to AR—and its upregulation following DNA damage—by radioimmunotherapy targeting of human kallikrein peptidase 2 (hK2)." (PMID 29691406, 2018). "The biology of the androgen receptor (AR) and its therapeutic importance have been investigated extensively in prostate cancer." (PMID 30547831, 2018). "The androgen receptor pathway has an integral role in prostate cancer biology and manipulating AR expression is a viable strategy to eradicate this disease." (PMID 29691406, 2018). "We and others have shown that chemical inhibition of LSD1 inhibits cell proliferation and AR signalling in prostate cancer cells." (PMID 29760584, 2018). "AR in prostate cancer is capable of exerting overwhelmingly and multifaceted oncogenic activities, including the promotion of glucose metabolism." (PMID 30478344, 2018). "Levels of HSP70 and AR-FL are significantly upregulated in metastatic castration-resistant prostate cancer (mCRPC) patients compared to benign prostate and primary prostate cancer in four independent GEO databases." (PMID 30446660, 2018). "The standard treatment of prostate cancer involves androgen derivation therapy in conjunction with small molecule antiandrogens that block AR signaling." (PMID 30210333, 2018). "LNCaP prostate cancer cells were originally derived from human metastatic lesions in lymph nodes, and they have an active AR and respond to androgen stimulation (androgen-dependent)." (PMID 30241348, 2018). "There are several publications that suggest AR expression correlates significantly with cancer stem cells mainly in prostate cancers, but few is known about their correlations in breast cancers.." (PMID 29423076, 2018). "In our study, we validate that endothelial cell induced autophagy reduced PXN and ZYX expression in AR positive prostate cancer cells." (PMID 30200999, 2018). "Several aspects of the intracellular calcium regulation have been uncovered in recent studies of AR signaling in prostate cancer." (PMID 29921791, 2018). "Silencing p21WAF1/CIP1 increased expression of the androgen receptor in prostate cancer cells, thereby stimulating expression of the viral E1A gene driven by the used androgen receptor-dependent prostate-specific promoter." (PMID 30477117, 2018). "We have deployed molecular targeting in our pharmacologic strategy to treat prostate cancer by exploiting upregulation of the androgen receptor (AR), a central oncogenic driver of the disease." (PMID 29691406, 2018). "Blocking the AR pathway in prostate cancer patients can be achieved by several mechanisms including surgical orchiectomy or chemically with luteinizing hormone-releasing hormone (LHRH) agonists, LHRH antagonists, or anti-androgens." (PMID 29339807, 2018). "Our results add another GEF in the growing list of GEFs that play important roles in prostate cancer and regulation of AR activity." (PMID 30558664, 2018). "In this report, we show that androgens and NGF both induce a reciprocal cross-talk between androgen receptor (AR) and TrkA in prostate cancer-derived LNCaP cells." (PMID 29531802, 2018). "Androgen receptor (AR) plays a critical role not only in the development of prostate cancer but also in the progress of the advanced castration states." (PMID 30210333, 2018).
prostate carcinoma (continued). "Therapeutics for late stage prostate cancer, such as enzalutamide and abiraterone, target the activity of the androgen receptor by blocking androgen synthesis or androgen/AR binding." (PMID 29308092, 2018). "FOXA1, as a nuclear receptor regulatory factor, is not limited to ERα as it also interacts with the androgen receptor (AR) to regulate its deposition to chromatin in prostate cancer cells." (PMID 30139998, 2018). "Numerous studies indicate that prostate cancer is driven by the androgen receptor (AR), a ligand-dependent transcription factor belonging to the nuclear receptor family." (PMID 29734647, 2018). "The BET bromodomain inhibitor JQ1 induced apoptosis and downregulated AR-regulated gene transcription by preventing the interaction between the BET protein BRD4 and the AR in prostate cancer cells, thus reducing xenograft tumor volume in mice." (PMID 29371637, 2018). "It would be interesting to explore the influence of SETD7 over NFκB and ERα, as well as AR transrepression and positive cross-talk as these pathways play key roles in breast and prostate cancer." (PMID 30013796, 2018). "In prostate cancer, KAT3B promotes tumor growth and activation of androgen receptor weakens invasiveness in melanoma, breast, and prostate cancer cell lines." (PMID 29632619, 2018). "To further test the TF enrichment, we carried out ChIP assays, followed by quantitative PCR and confirmed the chromatin binding of prostate cancer master regulators AR, FOXA1, and HOXB13 at the SNP site." (PMID 29789573, 2018). "We also confirmed the correlation between AL121790.1 and AR activity and additionally performed AR chromatin immunoprecipitation sequencing (ChIP-seq) on the prostate cancer cell line LNCaP treated with R1881 (a synthetic testosterone analog)." (PMID 30272002, 2018). "The notion that androgens and androgen receptor (AR) signaling are the hallmarks of prostate cancer oncogenesis and disease progression is generally well accepted." (PMID 29346310, 2018). "Mechanistically, we can conclude that UCM 1037 melatonin derivative inhibits androgen-sensitive prostate cancer cells growth, exerts a cytotoxic effect, down-regulates AR levels and Akt activation, possibly via a melatonin receptor-independent mechanism." (PMID 29783631, 2018). "Another example is that the androgen receptor-AMP-activated protein kinase (AMPK) signaling axis increased expression of PGC-1α to drive growth advantages in prostate cancers." (PMID 29599799, 2018). "Together with the AR, the oncogenic pathways most frequently altered in prostate cancer onset and progression are the RB, PI3K/AKT, and Ras/Raf pathways due to mutations in several members." (PMID 29888169, 2018). "Aberrant AR splicing patterns in prostate cancer has been identified as a key mechanism leading to acquired resistance to androgen ablation therapy." (PMID 30463359, 2018). "IL-8 affects androgen independence and IL-6 induces androgen receptor activation during prostate cancer cell progression." (PMID 30119678, 2018). "We report the development of the first high-throughput CETSA assay (CETSA HT) to identify direct AR binders in a prostate cancer cell line endogenously expressing AR." (PMID 29317749, 2018). "By targeting XPO1/ARv signaling, SINE suppressed prostate cancer (PCa) growth in vitro and in vivo and potentiated the anti-cancer activity of anti-AR agents, enzalutamide and abiraterone." (PMID 30450161, 2018). "A number of observations have described sensitivity of AR-resistant prostate cancer cells to death induced by certain triggers such as TWEAK, sorafenib, olaparib, and inhibition of BET proteins or PLK1, among others." (PMID 29371637, 2018).